DDX5 (DEAD-box helicase 5)
Diseases named in the same sentence as DDX5 in open-access papers (continued):
Sharing a sentence is not in itself a finding about the gene and the disease.
cancer (continued). "Network analysis indicates that DDX5, LIFR, ZEB2, mir-21, mir-27b, mir-30a, mir-141, mir-182 and mir-200c were shared across different constructed networks, indicting their crucial role in cancer biology and progression, which has been reported previously." (PMID 24796549, 2014). "With its tumor-restricted activity and far-reaching regulatory roles, DDX5 inhibition offers the prospect of reshaping therapeutic paradigms—not only in pediatric RMS, but across a spectrum of DDX5-dependent malignancies—paving the way for more precise, mechanism-based cancer therapies." (PMID 40950397, 2025). "Genes such as RLIM, FBL17, FGF7, DDX5, NAV3, and NFASC were found at the intersection of multiple pathways, suggesting they may function as critical effectors of miR-155 and miR-3173 activity in cancer." (PMID 40722677, 2025). "Notably, a similar change occurred in noncancer MRC‐5 cells, indicating that the hypoxia‐mediated repression of DDX5 is not restricted to cancer cells." (PMID 37013907, 2023). "Interestingly, this is an example for DDX5 to act as a transcription co-repressor (in immune Treg cells) but not a transcription co-activator (in cancer cells)." (PMID 37596619, 2023). "Another possibility for the role of DDX5 observed in HCC which is not fully consistent with other cancer types could be the DDX5-mediated overall gene expression-collective outcome." (PMID 37596619, 2023). "Kaplan-Meier survival analysis of TCGA data revealed that a higher expression of DDX5 mRNA was correlated with a negative prognosis in certain cancers, including LGG, GBMLGG, and ACC, and an improved prognosis in other cancer types, including COADREAD and KIRC." (PMID 36313454, 2022). "Thus, the important roles of DDX5/DDX17 in the body are self-evident and may be potential targets in cancer treatment." (PMID 35992805, 2022). "At stage 3, however, all these 26 defined TS genes have S > 0, suggesting that all these 26 TS genes had larger positive network effects on gene down-expression in cancer than negative network effects on gene up-expression even though APC, EXT1 and DDX5 had very small S-scores." (PMID 33580150, 2021).
tumor (78 papers, 2014 to 2026). "C1 SRSF7+ MC highly express DDX5, which had been shown to be associated with a variety of key tumor promoting molecular interactions and was involved in tumorigenesis and tumor progression signaling pathways." (PMID 39430754, 2024). "Analyses of normal human liver and HCCs showed that reduced DDX5 expression was associated with increased tumor grade and worse overall survival of patients treated with sorafenib." (PMID 38036507, 2023). "In clinical HCC samples reduced expression of DDX5 was associated with advanced tumor grade, and worst patient survival following treatment with sorafenib." (PMID 38036507, 2023). "This interaction indicates that high levels of DDX5 are associated with tumor development and suggests the oncogenic role of DDX5 in OS." (PMID 35954483, 2022). "On the other hand, overexpression of DDX5 caused a proliferation of keratinocytes thus confirming its role in tumor phenotypes of these cells." (PMID 35237661, 2022). "Our studies indicated that in human PDAC and CRC tumour models, high DDX5 expression is associated with high sensitivity of tumours to FL118 treatment." (PMID 35604033, 2022). "In order to investigate the molecular processes underlying the effects of DDX5 in tumor growth, we performed pathway enrichment analyses and analyzed the genes related to DDX5 expression and the genes that encode DDX5-binding proteins." (PMID 36313454, 2022). "We have used both human PDAC and CRC tumour models to determine the association of DDX5 expression and tumour sensitivity to FL118 treatment." (PMID 35604033, 2022). "Also, the extrachromosomal circular miR17–92 amplicon, encoding the mir17-92 miRNA cluster that downregulates various tumor suppressors including DDX5, was shown to be linked to poor prognosis HCC." (PMID 38036507, 2023). "Thus, enhanced sorafenib anti-tumor efficacy is achieved either by inhibiting the Wnt/β-catenin pathway activated by DDX5 loss or by overexpression of DDX5." (PMID 38036507, 2023). "Specifically, the expression of DDX5 is associated with a reduced infiltration of M2 macrophages and an increased infiltration of T cell clusters, which may contribute to anticancer effects in the tumor microenvironment." (PMID 38136426, 2023). "Specifically, the expression of DDX5 is associated with the reduced infiltration of M2 macrophages and increased infiltration of T cell clusters, which may contribute to anticancer effects in the tumor microenvironment." (PMID 38136426, 2023). "Interestingly, even though further experiments are required because of potential contradictory reported data, high Ddx5 expression level could be associated with higher tumor grade or poor prognosis in ER-positive breast cancer patients." (PMID 24275493, 2014). "Supinoxin (RX-5902), a selective small-molecule inhibitor of DDX5, exhibits strong anti-tumor activity." (PMID 41874163, 2026). "On the other, DDX5 cooperates with the m6A reader YTHDC1 to drive the biogenesis of a tumor-specific subset of circular RNAs (circRNAs), which further contribute to RMS pathogenesis." (PMID 40950397, 2025). "Given its pleiotropic roles in promoting tumor growth and resistance, further exploration of DDX5 in RMS is warranted, both to better understand its biological relevance and to evaluate its potential as a therapeutic target." (PMID 40950397, 2025). "Among them, DEAD-box RNA helicases play an important role in carcinogenesis and tumour metastasis, the most representative of which is DDX5." (PMID 40386063, 2025). "Clinical data also support these mechanistic results, revealing a correlation between reduced DDX5 protein levels, advanced tumor grade, and poor patient survival post-sorafenib treatment." (PMID 39122708, 2024).
tumor (continued). "MIR17HG RNA encodes the proto-oncogenic miR17 ~ 92 cluster, which, along with its paralog miR106b-25, both elevated in human HCCs, downregulate the expression of various tumor suppressors, including DDX5." (PMID 39122708, 2024). "The overexpression of DDX5 in Huh7 xenografts not only suppressed tumor growth following sorafenib treatment but also repressed the protein level of p62/SQSTM1, a positive upstream effector of NRF2 stability." (PMID 39122708, 2024). "A helicase defective mutant DDX5(K144R) resulted in similarly enhanced E2F1-mediated activation of tumor suppressor genes compared to wild-type DDX5, suggesting that DDX5 coactivator function is independent of its helicase activity." (PMID 39769018, 2024). "The existing literature has reported the contribution of DDX5 in cellular proliferation, differentiation, migration, and apoptosis across various tumor types." (PMID 39193132, 2024). "Conversely, overexpression of DDX5 in vivo enhances the anti-tumor efficacy of sorafenib by suppressing Wnt/β-catenin activation and induction of ferroptosis." (PMID 38036507, 2023). "O-GlcNAcylation of DDX5 facilitates tumor development; and methylation of DDX5 is related to R-loop resolution." (PMID 38023215, 2023). "IHC of DDX5 showed a higher number of nuclei with “diffuse”/less intense DDX5 staining in sorafenib-treated tumors than in peri-tumor, consistent with reduced DDX5 mRNA levels in sorafenib-treated tumors, but not in the peri-tumoral tissue." (PMID 38036507, 2023). "In tumor cells, DDX5 promotes Wnt signaling, angiogenesis and integrin signaling, while suppressing transmembrane transport, cytokine signaling and metabolism (Fig. 6B3)." (PMID 37596619, 2023). "Conversely, an increased infiltration of T cells was evident in tumors high in DDX5 compared with their low-DDX5 counterparts, indicative of a potential influential role of DDX5 expression in modulating immune cell infiltration in the tumor microenvironment." (PMID 38136426, 2023). "Kyoto Encyclopedia of Genes and Genomes (KEGG) pathway enrichment analysis also revealed that a lot of DDX5-regulated circRNAs are mainly enriched in tumor-related signaling pathway, including VEGF and insulin signaling pathway." (PMID 36996491, 2023). "DHX9 family members, such as DDX1, DDX3, and DDX5 are considered as oncogenes to promote proliferation of tumor cells." (PMID 37305700, 2023). "In all three tumor types, an inverse correlation was observed between hypoxia (pimonidazole positive) and DDX5 expression, confirming that hypoxia represses DDX5 protein expression in vivo." (PMID 37013907, 2023). "DDX5/DDX17 interact with many key tumor signaling molecules and participate in a variety of tumor-regulated signaling pathways, such as DNA damage repair, autophagy, oxidative stress and energy metabolism." (PMID 35992805, 2022). "The differences in the phosphorylation of DDX5 protein between primary tumor tissues and normal matched tissues were determined in this study." (PMID 36313454, 2022). "These variations in the same DDX5 KO clone suggest that individual mice can have different tumour formation and growth acceptability (tumour‐host effects)." (PMID 35604033, 2022). "This demonstrated an intriguing approach for FL118 to treat PDAC/CRC tumours with low DDX5 expression." (PMID 35604033, 2022).
tumor (continued). "Our studies of three available pairs of clinical non‐tumour adjacent (Non) and CRC tumour (Tu) specimens using western blot analyses indicated that two of the three CRC tumours showed enhanced DDX5 expression." (PMID 35604033, 2022). "We additionally identified a correlation between the expression of DDX5 mRNA and T-stage in certain tumor types." (PMID 36313454, 2022). "Here, we further show that PDAC PDX19015 and PDX17624 tumours with moderate expression of DDX5 were regressed after one cycle of FL118 treatment." (PMID 35604033, 2022). "The alterations in the DDX5 gene in the different tumor types in TCGA were predicted using the cBioportal webtool." (PMID 36313454, 2022). "The phosphorylation sites in the DDX5 protein were reviewed, and the differences between tumor and normal matched tissues were determined." (PMID 36313454, 2022). "DDX5 or DDX17 also participate in other tumor regulatory signaling pathways, such as DNA repair, oxidative stress, autophagy, and energy metabolism." (PMID 35992805, 2022). "For example, the C2‐1 clone tumour in different individual mice exhibited different tumour growth rates, even though it was the same DDX5 KO cell clone (C2‐1)." (PMID 35604033, 2022). "Nevertheless, it is likely that FL118 alone would eliminate some PDAC and CRC tumours, while FL118 in combination with an appropriate chemotherapeutic agent would eliminate some other PDAC and CRC tumours with low levels of DDX5 expression." (PMID 35604033, 2022). "SNRPD3 and U2AF2 showed (50%) the highest association; DDX5, DDX17, and SNRPF in between (40–50%) with neoplasm class." (PMID 34918006, 2022). "Upregulation of DDX5 leads to poor patient outcomes through the promotion of tumorigenesis and tumor recurrence." (PMID 36761420, 2022). "The different tumor types in TCGA were included in the clinical correlation analysis, and the findings revealed that the expression of DDX5 mRNA differed significantly among ACC, THCA, LUAD, KIRP, and the normal matched tissues (p < 0.05)." (PMID 36313454, 2022). "Data from the Human Protein Atlas Database have documented that DDX5 expression is enhanced in 83% of PDAC tumours." (PMID 35604033, 2022). "We observed that the infiltration levels of Tcm and Th cells was high in all the tumors at high expression levels of DDX5, which suggested that the DDX5 gene plays a potential role in the tumor immune microenvironment." (PMID 36313454, 2022). "Silencing or knockout (KO) of DDX5 in PDAC cells resulted in significant tumour growth retardation and increased PDAC cell resistance to FL118 treatment (i.e., significant loss of FL118's antitumour activity)." (PMID 35604033, 2022). "The cellular enzymes DDX3X and DDX5 play important roles in the maintenance of normal cell metabolism, but their deregulation can accelerate tumor transformation." (PMID 35954483, 2022). "For instance, H-Ras, CD44, PXN-AS1, macroH2A1, etc., are important tumor-related factors; therefore, the dysregulation of DDX5/DDX17 action is closely related to tumorigenesis and tumor progression." (PMID 35992805, 2022). "Specifically, we demonstrated that the silencing of DDX5 delays PDAC tumour growth, while the OE of DDX5 increases FL118 efficacy to inhibit PDAC cell growth." (PMID 35604033, 2022). "MicroRNA-493-5p (miR-493-5p) was a tumor repressor in NSCLC progression by targeting integrin beta-1 (ITGB1) or DEAD-box helicase 5 (DDX5)." (PMID 34537072, 2021). "When DRD2 located in cellular membrane, it exerted anti-tumor effects through downregulating DDX5 and eEF1A2." (PMID 33859743, 2021). "Immunohistochemical staining for DDX5 in tumor tissues showed a significant reduction in DDX5 expressions in Huh7 with DDX5-KD and in mice treated with STA9090." (PMID 33764710, 2021). "In the present study, we found that DDX5 protein was increased in HCC patients with high heat shock protein 90 (HSP90) expression, and was associated with higher tumor recurrence." (PMID 33764710, 2021).
tumor (continued). "In summary, our results have demonstrated that higher O‐GlcNAcylation and DDX5 levels significantly contributed to tumour proliferation and metastasis and indicate a poor prognosis in patients with CRC." (PMID 30484950, 2019). "DDX5 exhibited clear cell cycle-related localization in the nucleus, and its expression was related to tumor progression and transformation." (PMID 30185232, 2018). "NEAT1 activated the transcriptional activity of β-catenin to promote CRC tumor progression in a DDX5-mediated manner." (PMID 30185232, 2018). "The result showed that DDX5 expression was significantly decreased in tumor tissues down-regulating MIAT." (PMID 29540201, 2018). "Our results suggest that NEAT1 promotes CRC tumor growth and metastasis by stabilizing the DDX5 protein, thereby activating β-catenin gene transcription." (PMID 30185232, 2018). "We demonstrate for the first time that DDX5 is a primary target of resveratrol in tumor suppression." (PMID 27148684, 2016). "Together, these findings underscore how DDX5 functions as a signaling-responsive regulator whose impact depends on tumor context, upstream modifiers, and expression level—features that may critically influence responsiveness to targeted inhibition." (PMID 40950397, 2025). "Interaction analyses suggested that hsa_circ_0001038 may act as a molecular sponge for miR-205-5p, a tumour-suppressive miRNA, thereby potentially modulating DDX5 expression." (PMID 41303368, 2025). "CircRNAs themselves have been implicated in oncogenic processes in RMS, and the study by Dattilo and colleagues provides important mechanistic insights by demonstrating that YTHDC1 and DDX5 act cooperatively to drive the biogenesis of tumor-promoting circRNAs in this context." (PMID 40950397, 2025). "Importantly, this effect appears to be tumor-specific, as DDX5 depletion in human skeletal muscle myoblasts (HSMMs) does not impact their viability or proliferation." (PMID 40950397, 2025). "In addition, β-catenin directly induces DDX5 expression, forming a positive feedback loop that promotes tumor progression." (PMID 39781348, 2025). "Interestingly, DDX5 has been reported to regulate tumor cell cycle progression, which is consistent with our results." (PMID 41263459, 2025). "Herein we showed that DDX5 contributes to the tumor suppressive functions of deregulated E2F1." (PMID 39769018, 2024). "Considering that the depletion of YTHDC1/DDX5 reduces cell proliferation and that many circRNAs are involved in the control of cell growth, we speculate that the modulation exerted by YTHDC1 and DDX5 may act as an oncogenic feature in this tumor." (PMID 37019933, 2023). "Furthermore, DDX5 silencing blocked in vivo tumor growth in a murine HCC xenograft model; and high levels of HSP90 and DDX5 were associated with poor prognosis indicating a potential therapeutic biomarker target for HCC." (PMID 37596619, 2023). "Thus, succinate at least partially rescues DDX5 deletion-induced tumor formation inhibition (Fig. 6B2)." (PMID 37596619, 2023). "Notably, the upregulated DDX5 mRNA levels in PCa correlate with increasing tumor grade, both when compared with the normal tissue and when compared among the tumors of varying grade." (PMID 37596619, 2023). "Additionally, we observed several cell-type-specific deMuts involved in the spliceosome gene set (GSEA: KEGG pathway), such as SRSF3 and HNRNPC mutants in tumor cells and DDX5 mutants in endothelial cells." (PMID 37433798, 2023). "Normal levels of miR-671-5p downregulate DDX5 and prevent tumor progression." (PMID 35954483, 2022).